MTOR (mechanistic target of rapamycin kinase)
Diseases named in the same sentence as MTOR in open-access papers (continued):
Sharing a sentence is not in itself a finding about the gene and the disease.
cancer (continued). "The PI3K/AKT/mTOR pathway is a key signaling cascade that is overactivated in inflammatory diseases and cancers, leading to exacerbated immune responses and chronic inflammation." (PMID 40077417, 2025). "The PI3K/Akt/mTOR pathway is involved in the cell cycle, proliferation, cancer, and in some types of pain, mainly neuropathic pain." (PMID 39851421, 2025). "In OSCC, B7-H3 has been shown to support tumor growth by inducing aerobic glycolysis in cancer cells through upregulating the PI3K/Akt/mTOR signaling pathway." (PMID 40801642, 2025). "Oxamic acid-mediated inhibition of lactate dehydrogenase has been shown to reduce glycolysis and mTOR-dependent metabolic reprogramming in cancer cells." (PMID 41146185, 2025). "Activation of the mTOR signaling pathway is common in multiple human cancers such as breast, prostate, bone, lung, and colon." (PMID 40702333, 2025). "Nanoparticle-based systems present a promising strategy to enhance the effectiveness of cancer therapies by selectively influencing the PI3K/AKT/mTOR pathway and other tumor-promoting processes, thereby overcoming the limitations of conventional treatments." (PMID 40076496, 2025). "The GAS5/miR-222 axis also regulates the PTEN/AKT/mTOR pathway to suppress the progression of other cancers, such as papillary thyroid carcinoma, human B lymphocytic leukemia, and gastric cancer." (PMID 39941145, 2025). "In conclusion, the PI3K/Akt/mTOR pathway remains a cornerstone of cancer biology and a critical target for therapeutic intervention." (PMID 40080721, 2025). "Deregulation of the mechanistic target of the rapamycin (mTOR) pathway plays an important role in cancer genesis and progression, making it an attractive target for cancer treatment." (PMID 40717210, 2025). "Initially, pharmacological mTOR signaling inhibitors have been used after transplantation and cancer treatment." (PMID 41155356, 2025). "These factors then stimulate the I3K/Akt/mTOR/S6K signaling pathway, which is crucial in cancer progression." (PMID 39361532, 2025). "The PI3K/AKT/mTOR signaling pathway is one of the most frequently dysregulated pathways in human cancers." (PMID 41298358, 2025). "Ellagic acid and its metabolites have been shown to suppress AKT phosphorylation and downstream mTOR signaling in various cancer cell models." (PMID 41226270, 2025). "Autophagy-related proteins, including ATG4D, have been associated with the regulation of EMT and interactions with key signaling pathways, such as mTOR, that regulate cancer progression." (PMID 40630202, 2025). "As a result, the PI3K/AKT/mTOR pathway has become a key target in cancer therapy, driving considerable efforts to develop inhibitors that can disrupt its individual components to suppress tumor progression." (PMID 41303544, 2025). "Nanoparticles can improve siRNA and gene therapy delivery to the PI3K/AKT/mTOR-mediated autophagy pathway in cancer treatment." (PMID 40076496, 2025). "The PI3K/AKT/mTOR pathway is a key regulator of cancer progression, influencing various cellular processes, including autophagy." (PMID 40076496, 2025). "Recent clinical data for multi-node PI3K/mTOR/AKT pathway inhibition approaches has shown promising efficacy signals in cancer patients." (PMID 40360883, 2025). "Although the regulation of the PI3K/AKT/mTOR axis in the treatment of cancer by natural and small molecules will be discussed in the next sections, the current findings support the notion that PI3K/AKT/mTOR‐driven autophagy can be therapeutically modulated." (PMID 40740483, 2025). "The induction of oxidative stress has also been observed with other anti-cancer agents targeting the PI3K/AKT/mTOR, MEK/ERK, and STAT3 signaling axes, although effects differ between model systems." (PMID 40563571, 2025).
cancer (continued). "There was also significant upregulation of RAF and MTOR signalling, which are often modulated during cancer progression." (PMID 40434957, 2025). "The PI3K/AKT/mTOR signaling pathway plays a central role in orchestrating cancer cell metabolism, integrating signals to regulate glycolysis, lipid synthesis, protein synthesis, and amino acid metabolism." (PMID 41281744, 2025). "Given mTOR’s role in both cell destruction and growth pathways, its involvement in cancer formation has been discussed in great detail in several prior reviews." (PMID 40943615, 2025). "Dysregulation of this pathway—through overactivation of PI3K, AKT, or mTOR—is commonly observed in cancers, leading to resistance to apoptosis, uncontrolled cell growth, and therapy resistance." (PMID 40006976, 2025). "Among the molecular markers analyzed, the EMT transcription factor SNAIL—which plays a critical role in cancer cell invasion and metastasis—and mTOR exhibited significantly elevated expression in metastatic lesions from patients who experienced recurrence." (PMID 40566531, 2025). "For example, the activation of ATF4 expression in cancer cells inhibits the AKT/mTOR signaling pathway, leading to cell cycle arrest and autophagy." (PMID 40416391, 2025). "Conclusively, STAT3 seems to be one of the major downstream effectors of BCP in regulating a complex network, including NF-κB and PI3K/AKT/mTOR and other cell cycle and apoptosis regulatory molecules in cancer." (PMID 40333803, 2025). "In previous studies, we observed that when autophagy was induced in cancer cells responding to anticancer drugs, mTOR was activated in those cells." (PMID 40848971, 2025). "The PI3K/AKT/mTOR pathway is frequently overactive in cancer cells, resulting in unchecked cell survival, growth, and proliferation." (PMID 41041347, 2025). "Since the function of the mTOR pathway is often dysregulated in cancer cells, drugs targeting mTOR have become a valuable therapeutic option in these cancers." (PMID 41375037, 2025). "Apoptosis can be regulated by the PI3K/AKT/mTOR axis in human cancers, and its dysregulation further enhances tumorigenesis." (PMID 40740483, 2025). "Similar to rapamycin, everolimus induces AKT activation while inhibiting mTOR signaling in human cancer cells, including NSCLC cells, as well as in tumor biopsies." (PMID 40041495, 2025). "Rapamycin and its analogs are highly selective inhibitors of mTOR and are already used clinically for the treatment of cancer, but an important aspect should be considered in the treatment of AD." (PMID 40357169, 2025). "According to previous studies, the interaction between WNT and mTOR signaling influences tumor metabolism, cancer cell growth, and spermatozoa formation." (PMID 40011822, 2025). "Shang demonstrated that SJZD induces autophagy and apoptosis in HCT116 and LOVO cancer cells by modulating PI3K/Akt/mTOR signaling in CRC." (PMID 40182845, 2025). "Macropinocytosis and MTOR signaling pathway are deeply intertwined, and their reciprocal regulation plays a pivotal role in cancer metabolism and tumor progression." (PMID 39817564, 2025). "The PI3K/AKT/mTOR pathway plays a crucial role in regulating cell proliferation and survival, especially in cancer cells." (PMID 41348684, 2025). "Numerous key pathways linked to the development of cancer, including the PI3K/Akt/mTOR signaling pathway, which is necessary for cell proliferation and survival, are inhibited by coumarin." (PMID 39803273, 2025). "In cancer, hyperactivation of mTOR drives protein translation and anabolism, supporting cancer cell proliferation." (PMID 40823305, 2025).
cancer (continued). "Phosphorylation of Akt and mTOR was significantly lower in the cancer cachexia group than in the sham group, while LJFE‐E treatment ameliorated the decrease in the phosphorylation of Akt and mTOR." (PMID 40672545, 2025). "Numerous signaling pathways, including EGFR-ERK1/2, MAPK, PI3K, and mTOR, play a crucial role in controlling cell proliferation, growth, and survival, as well as interrupted in various forms of cancer." (PMID 40487371, 2025). "Further research with PI3K/AKT inhibitors or siRNA trials is required to demonstrate a link between plant bioactive compounds and the mTOR pathway, offering light on their potential function in cancer treatment." (PMID 40717210, 2025). "PI3K inhibition can effect diverse cellular changes in oncogene-addicted cancers, including mTOR-dependent down-regulation of MCL-1 protein levels, which we confirmed." (PMID 40316540, 2025). "For example, CDDO-Im regulates apoptosis and the cell cycle in cancer cells, unfolded protein responses and other immune pathways including the mammalian target of rapamycin (mTOR) pathway." (PMID 40563311, 2025). "PIK3CA is an oncogene whose aberrant expression can lead to increased phosphorylation of AKT and subsequent activation of the PI3K/Akt/mTOR signaling pathway, which promotes cancer cell survival and proliferation." (PMID 40725233, 2025). "Several methods are used to monitor mTOR in cancer, including molecular profiling, biomarker analysis, imaging techniques, and so on." (PMID 40717210, 2025). "Despite their improved potency, both ATP-competitive mTOR inhibitors and dual PI3K-mTOR inhibitors fail to fully overcome the resistance mechanisms of classical mTOR inhibitors, underscoring the complexity of targeting mTOR signalling in cancer therapy." (PMID 40805230, 2025). "The interaction of nanoparticle signaling with the PI3K/AKT/mTOR and autophagy pathways highlights the dual function of autophagy in cancer, serving as both a pro-survival mechanism and a facilitator of apoptosis." (PMID 40076496, 2025). "In contrast, our Mendelian randomization (MR) study provides genetic evidence supporting the use of mTOR inhibitors in the treatment of non-cancer diseases." (PMID 40299431, 2025). "By inhibiting the mTOR signaling pathway, apigenin promotes autophagy-mediated cell death, thereby limiting cancer cell survival under metabolic or oxidative stress." (PMID 40490812, 2025). "This analysis revealed that the co-expressed and co-methylated lncRNAs are associated with seven key cancer-related signaling pathways: Hippo, MAPK, Wnt, adherens junction, focal adhesion, PI3K-Akt, and mTOR." (PMID 40350996, 2025). "The mammalian target of rapamycin (mTOR) is a protein kinase that plays a pivotal role in key functions implicating in cancer pathogenesis and therefore comprises a therapeutic target." (PMID 40055269, 2025). "Dysregulation of the PI3K/AKT/mTOR pathway is frequently noted in cancer, resulting in unregulated cell proliferation, survival, and resistance to therapy." (PMID 40076496, 2025). "Stabilizes the PI3K/Akt/mTOR pathway signaling protein Akt, maintaining its cellular levels, thereby influencing cancer cell survival." (PMID 39936995, 2025). "The convergent surviving cell gene set we identified indicated that pro-survival and anti-apoptotic pathways, such as TNFα via NFkB, PI3K-AKT, and mTOR signaling, are upregulated in polyploid cancer cells." (PMID 39578659, 2025). "In veterinary medicine, cancer therapy targeting the PI3K/AKT/mTOR signaling pathway is expected to exhibit antitumor effects against canine mammary cancer, hemangiosarcoma, and melanoma." (PMID 40563640, 2025). "On the other hand, since mTOR inhibitors are also actively studied to promote lifespan and in cancer treatments, the clinical relevance of this finding in our study is unclear at the moment and would require further study." (PMID 40280130, 2025).
cancer (continued). "The effect of the mTOR protein, which is essential for the development of cancer, was further investigated in a computational study." (PMID 41164768, 2025). "This activation has led to multiple studies evaluating targeted therapies against the PI3K/AKT/mTOR pathway, with mixed results depending on the cancer type." (PMID 39941724, 2025). "The PI3K/Akt/mTOR signaling pathway is commonly deregulated in different types of cancers, contributing to tumor proliferation, persistence, and resistance to treatment." (PMID 40798865, 2025). "Mechanistically, cancer cell proliferation is largely driven by dysregulated activation of the PI3K/Akt/mTOR signalling pathway, which regulates cell metabolism, growth, survival, and motility." (PMID 41002741, 2025). "UBASH3B has emerged as a promising oncogenic target due to its involvement in a multitude of cancer-associated pathways, including PI3K/Akt/mTOR, MAPK, and JAK-STAT signaling." (PMID 40885971, 2025). "For example, Plumbagin can inhibit cancer cells growth via instigating PI3K/Akt/mTOR‐intervened G2/M phase cell arrest, apoptosis, and autophagy." (PMID 40347062, 2025). "The serine/threonine kinase mTOR, which regulates cell growth, survival, and metabolism, particularly in cancer cells, can be activated by the protein kinase AKT." (PMID 40969301, 2025). "Targeting the PI3K/AKT/mTOR signaling pathways has garnered significant interest in the treatment of cancer, including AML, resulting in the development of various small molecule agents." (PMID 40917720, 2025). "Everolimus and temsirolims are developed first-generation mTOR inhibitors and are approved by the Food and Drug Administration to treat several human cancers, such as renal-cell carcinoma." (PMID 40563640, 2025). "Emerging evidence has established the diverse therapeutic potential of flavonoids in cancer treatment through their interactions with multiple molecular targets within the PI3K/Akt/mTOR pathway." (PMID 40798865, 2025). "Rapamycin (mTOR Inhibitor) - used in rodent models to study ageing, cancer, and neurodegenerative diseases." (PMID 40097854, 2025). "Its activation leads to inhibition of the mTOR pathway, reduction in proliferation, reduction in mRNA translation and protein synthesis in cancer cells in vitro." (PMID 40468055, 2025). "Rapamycin directly inhibits mTOR, a key pathway involved in cell growth, proliferation, and inflammation, which are crucial in preventing chronic inflammation—a known contributor to cancer development." (PMID 39940361, 2025). "Aspirin pretreatment disrupts the binding of the TATA-box and p300 at the initiation region of the mTOR promoter in cancer stem cells (CSCs), thereby inhibiting the binding of RNA polymerase II at these sites and suppressing mTOR gene transcription." (PMID 40041495, 2025). "Targeting the PI3K/AKT/mTOR signaling pathway presents a promising strategy for cancer treatment; however, traditional therapeutics frequently encounter issues related to nonspecific distribution and systemic toxicity." (PMID 40076496, 2025). "BCAA metabolism supports cancer cell growth, survival, and proliferation by modulating pathways such as mTOR signaling and oxidative stress responses." (PMID 40438606, 2025). "Polymeric micelles enhance the therapeutic efficacy of chemotherapy by suppressing autophagy through the mTOR pathway, hence increasing the sensitivity of cancer cells." (PMID 40076496, 2025). "FAK mediates signalling from the ECM to the cytoplasm via several pathways, including the phosphatidylinositol 3-kinase (PI3K)/protein kinase B (AKT)/mechanistic target of rapamycin (mTOR) pathway that promotes cancer cell survival." (PMID 40527011, 2025).
cancer (continued). "The condition also contributes to major cancer pathways including the mTOR pathway, PI3K pathway, and AMP pathways." (PMID 41186627, 2025). "Guided by these results, we developed a highly multiplexed PRM assay for precise quantitation of 90 proteins that are associated with cancer metabolism, RNA regulation, and major cancer pathways, such as PI3K/AKT/mTOR and EGFR/RAS/RAF." (PMID 39723668, 2025). "Additional enriched pathways included cell cycle regulation (G1/S) and broader cancer signaling networks such as the MTOR pathway." (PMID 39974082, 2025). "Inhibiting this pathway through the use of NVP-BEZ235, which targets PI3K and mTOR, has shown promise in treating various cancers." (PMID 40771929, 2025). "This has led to the development of PI3K, AKT, and MTOR inhibitors for use in cancer patients, leading to multiple FDA approvals over the past decade." (PMID 40564038, 2025). "While we have demonstrated the potential of repurposing mTOR inhibitors for non-cancer applications and identified novel mTOR-related metabolites, immune traits, and gut microbiota, these findings need to be confirmed through experimental studies." (PMID 40299431, 2025). "The PI3K/Akt/mTOR pathway is frequently dysregulated in cancer, leading to uncontrolled cell proliferation, enhanced survival, and resistance to therapies." (PMID 40723802, 2025). "The combinations include EGFR inhibitor, IGF1-R/IR inhibitor, Akt inhibitor, and mTOR inhibitor that can directly or indirectly target different components of the PI3K/Akt/mTOR pathway a crucial signaling cascade in several cancers." (PMID 41427337, 2025). "Beyond its potential application in cancer, Compound 7 has shown promising results in models of neurological disorders, highlighting its role in regulating mTOR-dependent neurodevelopmental and neurodegenerative processes." (PMID 40386392, 2025). "Rapamycin (sirolimus) and its analogs, such as Everolimus and Temsirolimus, are used as mTOR (mammalian target of rapamycin) inhibitors in cancer treatment." (PMID 40429883, 2025). "The current classical approach to regulate the level of PTEN is to focus on the PI3K/AKT/mTOR signaling pathway, and numerous studies have found that PTEN mutation in the PI3K/AKT/mTOR pathway can drive cancer development." (PMID 40129459, 2025). "In fact, exercise-induced mTOR activation has been found to be related to the prevention of some types of cancer." (PMID 40944200, 2025). "According to reports, PD-1 pathway promotes cancer cell growth by activating downstream mTOR signaling, which is a master regulator of glucose metabolism by promoting HIF-1α expression." (PMID 40599793, 2025). "The Phosphatidylinositol-3-kinase (PI3K)/AKT/mammalian target of the rapamycin (mTOR) signaling (PI3K-Akt) pathway is an important biological pathway that plays a role in the progression of cancer." (PMID 40004558, 2025). "Phosphatidic acid is an important molecule for the stability and activity of the mTOR complex, a protein kinase that suppresses apoptotic signals in cancer cells." (PMID 39827162, 2025). "For example, inhibitors of mTOR are approved for the treatment of several cancers, including pancreatic neuroendocrine tumours, and they remain under investigation as PDAC therapies, although trials to date have yielded disappointing results." (PMID 40723241, 2025). "Various studies show the inhibition of the proliferation and metastasis properties of cancer cells when treated with sinulariolide through downregulation of PI3K/mTOR and p38MAPK pathways in bladder and hepatic cancer." (PMID 41321380, 2025). "MECOM has been previously linked with cancer stem cell properties, malignant transformation, cell proliferation and inhibition of apoptosis through the AKT/mTOR pathway." (PMID 39920655, 2025). "Everolimus, a significant mTOR inhibitor, has shown efficacy in reducing tumor growth and overcoming resistance to chemotherapy in cancer patients." (PMID 40769273, 2025).